MIF (macrophage migration inhibitory factor)
Diseases named in the same sentence as MIF in open-access papers (continued):
Sharing a sentence is not in itself a finding about the gene and the disease.
tumor (continued). "Rapid depletion of MIF from tumor cells observed immunohistochemically is coincident with elevated circulating MIF detected in the blood sera of irradiated mice." (PMID 26741693, 2016). "MIF was further shown to be upregulated in the tissue of different tumor types, i.e. pancreatic, breast, prostate, colon, brain, skin, and lung tumors." (PMID 27636991, 2016). "Exosomes released by tumor cells contain factors such as macrophage migration inhibitory factor (MIF) that influence the physiology of the recipient cells." (PMID 27092178, 2016). "MIF secreted by the tumor cells can promote the formation of new blood vessels and regulate the microenvironment of tumor cells, so as to avoid immune surveillance and promote the spread of tumor cells." (PMID 26911617, 2016). "During tumorigenesis, tumor cells secrete growth factors and cytokines (including MIF) which amplify tumor cell transformation, activate their proliferation and modify the activation state of surrounding inflammatory cells." (PMID 26883190, 2016). "MIF is a pro-inflammatory cytokine overexpressed in various tumors, where it promotes tumor growth and progression by the activation of multiple signaling cascades, including AKT pathway." (PMID 26871295, 2016). "Our group has recently shown that the majority of malignant mesothelial tumor cells express MIF and its receptor CD74, with a homogenous distribution between the different histological subtypes." (PMID 26883190, 2016). "The involvement of MIF in human tumor development has been substantiated by reports that describe higher MIF levels in the circulation of cancer patients." (PMID 27636991, 2016). "Macrophage Migration Inhibitory Factor (MIF) has for long been known to participate in tumor proliferation due to its pro-inflammatory cytokine functionality." (PMID 27392431, 2016). "IL-13, MCP-1 and MIF have been shown to induce infiltration of immune cells and promote tumour progression, −invasion and metastasis in various cancers." (PMID 27206490, 2016). "MIF is overexpressed in many tumor types, including pancreatic cancer, oral squamous cell carcinoma, melanoma, glioblastoma, and clear cell renal cell carcinoma (ccRCC)." (PMID 26741693, 2016). "Our data suggest a potential stromal role for DDX6 in the hypoxia response as an alternative to its previously established tumor-specific activity, and a potential link with MIF activity in the tumor." (PMID 26980748, 2016). "For total MIF, we again detected a moderate to strong uniform staining in tumor cells and tumor stroma of most tumor cores as well as in normal lung tissue." (PMID 27636991, 2016). "MIF expression level is correlated with the tumor microvessel density, and patients with positive MIF expression show a worse disease-free survival." (PMID 26911617, 2016). "As an inflammatory factor, a growing number of studies have shown that MIF is involved in tumor occurrence and development." (PMID 26911617, 2016). "We found, in a temporally coordinated manner, that there was a spike in circulating MIF at 2 hours, decreasing by 6 hours and returning to baseline levels at 24h, effectively mirroring the effect at the tumor tissue level." (PMID 26741693, 2016). "Tumor tissue sections stained for MIF showed a dramatic decrease in MIF staining at 30 minutes and 2 hours compared to unirradiated tumors, with a return to baseline levels at 24 hours." (PMID 26741693, 2016). "Tumorigenic 786-O cells were implanted into nude mice due to their rapid tumor growth and abundant MIF expression and allowed to grow to a size of ~1 cm3." (PMID 26741693, 2016). "Total MIF showed a moderate to strong uniform staining in each of the tumor cores (tumor cells and stroma) as well as in normal ovarian tissue." (PMID 27636991, 2016). "Macrophage migration inhibitory factor (MIF) deficient macrophages showed decreased immunosuppressive and pro-angiogenic gene expression with less tumor burden in mice." (PMID 27886105, 2016).
tumor (continued). "This demonstrated that the i.v. injection of the BG34-10-Re-I/(MIF-siRNA) nanoparticles result in the effective MIF protein reduction in TAMs within 4T1 tumor microenvironment." (PMID 25799489, 2015). "On the other hand, others have shown that the tautomerase activity of MIF is essential for tumor growth and metastasis, and the relationship between the tautomerase activity of MIF and its biological functions remains controversial." (PMID 26352431, 2015). "MIF has been identified as a major gene product up-regulated in disease tissue (such as tumor) where macrophages infiltrate and accumulate." (PMID 25799489, 2015). "Tautomerase-null MIF retains its ability to bind CD74 and CSN5 and the tumor forming capacity, indicating that the tautomerase activity of MIF is dispensable for its transformational function." (PMID 26352431, 2015). "MIF has been reported to play a central role in tumor cell proliferation and invasion in several cancers." (PMID 26530123, 2015). "MIF is considered a pluripotent cytokine and chemokine that plays a significant role in regulating immune responses of the tumor microenvironment." (PMID 25799489, 2015). "In HNSCC, tumor-derived MIF not only recruits TANs but also induced these cells to display promigratory effects on the tumor cells." (PMID 26819959, 2015). "Over-expression of MIF has been shown in several neoplasms and expression levels have been found to correlate with disease severity." (PMID 26352431, 2015). "CCL8 and CCL2 secreted by tumor cells were reported to recruit monocytic cells, and CXCL1 and MIF were linked to the recruitment of MDSCs." (PMID 25514599, 2015). "The cytoplasmic expression of MIF was found in the tumor cells of the lung, breast, liver, colon, and prostate." (PMID 26087187, 2015). "We examined cultured MTFs for expression of the pro-carcinogenic cytokine MIF, because of MIF’s prominent roles in M2 polarization of macrophages, the tumor microenvironment (TME), and cancer progression." (PMID 26267609, 2015). "MIF has been reported to be overexpressed in multiple cancers and its role in tumor cell proliferation has been documented." (PMID 26530123, 2015). "MIF tissue expression, quantified by a modified Allred score, was strongly increased in carcinoma compared to tumor-free specimens, in the cancer cells and in the peritumoral stroma, with fibroblasts the most intensely stained." (PMID 24939415, 2014). "We found that MIF and cyclin D1 were overexpressed in 71% (66/93) and 41% (38/93) of tumor samples, respectively." (PMID 25015194, 2014). "The therapeutic administration of the MIF inhibitor reduced tumor growth rates in all animals of the ISO-66-treated group." (PMID 25050663, 2014). "MIF is also quite known for inhibiting apoptosis, favoring cell survival and stimulating proteolysis, tissue remodeling and tumor invasion." (PMID 25329068, 2014). "In a MIF-null environment, tumor growth is significantly delayed and part of this effect is mediated by inefficient recruitment of pro-tumoral regulatory cell populations." (PMID 24406307, 2014). "This study also showed in mice that inhibition of MIF decreased metastasis of tumor cells injected into the tail vein." (PMID 24887129, 2014). "Our results are in agreement with previous reports showing that MIF hampers anticancer immunity by inhibiting tumor-specific CTL and NK cell activity." (PMID 25050663, 2014). "The tumor volume of mice injected with MIF siRNA showed significantly reduced tumor growth compared with the mice administered control siRNA." (PMID 25015194, 2014).
tumor (continued). "We observed an inverse correlation between stromal MIF expression and tumor size, as well as an elevated MIF presence in fibroblasts surrounding the tumor tissue." (PMID 24939415, 2014). "Neutralization of MIF by anti-MIF antibodies inhibited endothelial cell growth and led to a reduced number of tumor capillaries." (PMID 24770423, 2014). "In many cases, the degree of MIF overexpression is correlated with tumor progression and/or metastatic potential." (PMID 24586879, 2014). "In turn, increased MIF secretion by tumour cells contributed to metalloproteinase production by the macrophages and this augmented the invasive potential of the tumour cells." (PMID 25168062, 2014). "Our findings showed an increased extent of MIF expression in cancer cells and in stromal fibroblasts of BC tumor, in contrast to a less uniform increase of CD74 expression mainly in stromal lymphocytes, macrophages and endothelium." (PMID 24939415, 2014). "We evaluated the expression of MIF and cyclin D1 by performing immunohistochemistry on 93 tumor specimens from HCC patients." (PMID 25015194, 2014). "Colon tumor-derived fibroblasts produced approximately 260 pg/ml MIF while normal tissue-derived fibroblasts produced approximately 40 pg/ml of MIF." (PMID 24887129, 2014). "The important role of MIF in tumor progression has led to the development of MIF-antagonizing or MIF-neutralizing strategies for the treatment of cancer." (PMID 24406307, 2014). "A representative image shows reduced tumor growth in the MIF siRNA-treated group compared with the control siRNA-treated group." (PMID 25015194, 2014). "In cancer cells, MIF seem to play both an autocrine and paracrine role for tumor cell survival and invasiveness." (PMID 24406307, 2014). "MIF is thought to have tumor promoting properties so proliferation was examined here in several approaches." (PMID 24887129, 2014). "Taken as a whole, our results in conjunction with accumulated evidence from other cancer studies, suggest that selective MIF inactivation upon treatment with ISO-66 restores the lytic ability of tumor-reactive CTLs and NK cells, which become immunocompetent." (PMID 25050663, 2014). "Further, we wished to assess the molecular mechanisms responsible for the anti-tumor effects of functionally dampening MIF expression using specific siRNA sequences." (PMID 23522304, 2013). "Synchronous high levels of MIF and tumor-infiltrating neutrophils had stronger predictor values over the individual markers as well." (PMID 23409183, 2013). "In further studies, we combined the prognostic value of AHNAK with selected markers of inflammation, such as macrophage migration inhibitory factor (MIF) and tumor-infiltrating neutrophils (CD66b-positive cells)." (PMID 23409183, 2013). "A synergistic effect between cellular and molecular factors regarding tumor progression is supported by combined analysis of MIF and neutrophils in our cohort of patients." (PMID 23409183, 2013). "The statistical analysis showed a significant negative correlation between DFS, OS and the expression levels of MIF in tumor cells and TILs and CXCR4 in tumor cells (P < 0.05)." (PMID 23497377, 2013). "As a CLF chemokine, MIF acts as a chemoattractant for leukocytes, endothelial progenitor cells, and certain tumor cells, and mediates many pro-inflammatory processes through the induction of cytokines, chemokines, and adhesion molecules." (PMID 23720662, 2013). "Macrophage migration inhibitory factor (MIF) is another chemoattractant involved in tumor progression." (PMID 23673510, 2013). "The ability of MIF to suppress anti-inflammatory pathways is highly relevant to the growing appreciation of chronic inflammatory pathways promoting tumor growth and metastatic development." (PMID 23522304, 2013). "A number of studies found that high levels of MIF in the tumor tissues or serum of patients with different types of cancer associated with advanced disease and poor clinical outcome." (PMID 23409183, 2013).
tumor (continued). "Several reports in the literature have indicates the critical role of MIF as a regulator of innate and adaptive immunity, inflammation and tumor progression." (PMID 23522304, 2013). "Multivariate analysis showed that the expression of MIF or CXCR4 in tumor cells and the expression of MIF in TILs were adverse independent factors for disease-free survival (DFS) and overall survival (OS) in the whole cohort of patients (P < 0.05)." (PMID 23497377, 2013). "MIF secreted by tumor cells increased the macrophage metalloproteinase production rates and facilitated tumor cell invasion." (PMID 23673510, 2013). "CXCR4 is the receptor of stromal cell-derived factor-1 (CXCL12/SDF-1α) and can also bind to MIF, and takes an important role in tumor progression and anti-tumor immunity." (PMID 23497377, 2013). "In an attempt to elucidate the putative mechanisms responsible for the possible anti-tumor effect of MIF siRNA, we assessed the relative expression levels of proteins thought to be associated with apoptosis and cellular proliferation." (PMID 23522304, 2013). "As such, MIF mediates the recruitment of monocytes, T-cells, neutrophils, endothelial progenitor cells, and tumor cells." (PMID 23720662, 2013). "Our results from these experiments suggest that the combination of MIF and SCD1 is potentially useful as a prognostic marker associated with tumor progression or metastasis in patients." (PMID 24167613, 2013). "High MIF expression in tumor cells or in TILs or high CXCR4 expression in tumor cells was significantly related to poor survival of ESCC patients (P < 0.05)." (PMID 23497377, 2013). "Astrocytes in co-culture were activated by tumor cell-oriented factors, including macrophage migration inhibitory factor (MIF), IL-8 and plasminogen activator inhibitor-1 (PAI-1)." (PMID 23426399, 2013). "A major breakthrough in our understanding of the role of MIF in tumor metastasis in NSCLC was the identification of CD74 (the invariant chain of the HLA class II peptide) as the cell surface receptor for binding MIF." (PMID 23522304, 2013). "Here we review MIF actions with respect to redox regulation in apoptosis and in tumor growth as well as its extracellular function with a focus on its potential role in brain diseases." (PMID 22973314, 2012). "A significant amount of evidence indicates that MIF influences several important biological mechanisms and processes by which tumours thrive and spread." (PMID 23116199, 2012). "Even though the role of MIF in tumorigenesis has been reported in many different cancers, the significance of MIF in term of tumor survival is unclear." (PMID 22629429, 2012). "MIF protein is involved in many malignancies, as it promotes cellular transformation, inhibits cytolytic immune response against tumor cells and promotes neovascularization." (PMID 22461895, 2012). "It has recently been shown that the chaperone HSP90 stabilizes MIF for E3-ubiquitin-ligase-dependent proteasome degradation in various tumor cells, leading to increased MIF levels even under siRNA-mediated transcriptional silencing." (PMID 22973314, 2012). "Macrophage migration inhibitory factor (MIF) is considered as an important mediator in the pathogenesis of neoplasia." (PMID 21438767, 2011). "While IL-8-KD Daoy tumors induced murine RANTES RNA levels similar to those of un-manipulated Daoy, MIF-KD Daoy tumor RNA showed a 38-fold decrease in RANTES expression compared to parental Daoy tumors." (PMID 21647415, 2011). "To understand the antitumor effects of pNP73-102, we examined NPRA and MIF expression in TRAMP-C1-engrafted tumor lysates from representative control (pVAX) and pNP73-102-treated mice." (PMID 21586128, 2011). "In the present study, overexpression of MIF mRNA was found in HCC tissues compared with non-tumor tissues and correlated with the expression of MIF shown by immunohistology." (PMID 21438767, 2011).
tumor (continued). "This indicates that MIF, derived from tumor cells, is responsible for RANTES production by endothelial cells and subsequently, T lymphocyte migration." (PMID 21647415, 2011). "The TNF-α also induces tumour cell invasion through NF-κB- and JNK-mediated upregulation of migration-inhibitory factor (MIF) in macrophages and through enhanced MMPs production in tumour cells." (PMID 20087353, 2010). "Recently, it has been demonstrated that after chronic UVB irradiation, an early onset of carcinogenesis and a higher tumor incidence were observed in transgenic (Tg) mice overexpressing MIF mice compared to wild-type (WT) mice." (PMID 24281172, 2010). "It has also been reported that using an anti-MIF antibody is effective for reducing tumor growth and neovascularization in lymphoma cells and vascular endothelial cells in vivo." (PMID 24281172, 2010). "In both tumour cell lines, accumulated MIF concentrations in the supernatants reached appreciable concentrations, whereas no constitutive MIF release was observed in MCF-12A." (PMID 19602265, 2009). "Our study provides new insight into the role of MIF in tumor growth and progression by showing the importance of MIF for overcoming contact inhibition." (PMID 20038293, 2009). "Here we report for the first time a link between MIF and overriding contact inhibition in tumor cell lines." (PMID 20038293, 2009). "The cytokine MIF is increasingly appreciated to play a role in oncogenic transformation and the promotion of tumor growth in addition to a broad spectrum of pro-inflammatory actions in a range of tissues and inflammatory diseases." (PMID 19703290, 2009). "Although MIF expression was variable in both normal and malignant breast tissue, abundant MIF expression was predominantly found in tumour cells." (PMID 19602265, 2009). "We detected substantial but varying concentrations of MIF protein in essentially all tumour cells, where MIF was primarily localised in the cytosol." (PMID 19602265, 2009). "Suppression of MIF function by anti-MIF antibody treatment and MIF-antisense transfection alters the proliferate state of tumor cells in vivo and in vitro." (PMID 20038293, 2009). "Supporting this, recent studies have demonstrated a functional role for MIF in normal cell division as well as cell survival and oncogene-induced malignant transformation making this cytokine an important new focus in tumour biology research." (PMID 19703290, 2009). "MIF functions in multiple ways to boost tumor growth by promoting angiogenesis, stimulating cell cycle progression, inhibiting apoptosis and preventing NK cell lysis." (PMID 20038293, 2009). "In line with our results, secretion of MIF by tumour cells and autocrine stimulation of neoplastic behaviour by MIF has previously been observed for several tumour cell types." (PMID 19602265, 2009). "Secretion of MIF by tumour cells has been proposed to enhance tumour cell proliferation by autocrine amplification as known for other growth factors expressed by cancer cells." (PMID 19602265, 2009). "Overexpression of tumor cell-derived macrophage migration inhibitory factor (MIF) in solid tumors is related to tumor growth, progression, and angiogenesis." (PMID 19602232, 2009). "MIF is not only secreted by immune cells, but also by parenchymal and tumour cells upon inflammatory and stress stimulation." (PMID 19602265, 2009). "The possible inhibitory activity of ISO-1 on MIF-promoted tumor suppression has recently been described in two in vivo models." (PMID 20038293, 2009). "Recombinant MIF (rMIF) promotes cell proliferation and migration and blockade of MIF by antibodies or gene deletion leads to reduced proliferation and inhibition of tumour growth and angiogenesis." (PMID 19602265, 2009).